CAV1 (caveolin 1)
Diseases named in the same sentence as CAV1 in open-access papers (continued):
Sharing a sentence is not in itself a finding about the gene and the disease.
breast carcinoma (continued). "Mutant mice in the gene-encoding CAV-1 showed an enhanced association with the development and progression of breast cancer carcinogenesis and normally regulated the proliferation of intestinal stem cells in vivo." (PMID 28828003, 2017). "Prostate cancer is thus similar to breast cancer where decreased Cav-1 expression in the tumor stroma is associated with aggressive disease." (PMID 27764093, 2016). "CAV1 deficiency in breast cancer also promoted late stage autophagy by enhancing lysosomal function and autophagosome-lysosome fusion towards improved cell survival under nutrient starvation." (PMID 27852311, 2016). "In this regard, this study provides epidemiologic and mechanistic evidence indicating that the loss of Cav-1 expression promotes a form of metabolism that is permissive to breast cancer progression and, therefore, can negatively impact patient outcome." (PMID 26543228, 2016). "Similar reciprocal regulation was also observed between Cav-1 and c-ErbB2, a proto-oncogene encoding Her-2 in human breast carcinomas." (PMID 26431273, 2015). "Even in breast cancer, a strong association was found between elevated Cav-1 and a basal-like phenotype." (PMID 26431273, 2015). "We first examined the possible association of BKCa channels with caveolin-1 in human breast cancer MCF-7 cells." (PMID 25397596, 2014). "The loss and/or downregulation of the expression of caveolin-1 by stromal fibroblasts in breast cancer have been seen as an important biomarker that suggests poor survival." (PMID 24857919, 2014). "Loss of stromal Cav-1 is a single independent predictor of early breast cancer recurrence and progression." (PMID 24949874, 2014). "Loss of stromal Cav-1 is the single independent predictor of early breast cancer recurrence and progression." (PMID 24949874, 2014). "Caveolin-1 loss is reported to occur in 5–40% of all breast cancers, and therefore only a portion of breast cancers would be exhibiting the reverse Warburg effect." (PMID 25140630, 2014). "This notion is well in line with a recently published study demonstrating that caveolae-associated ANX2 along with caveolin-1 (Cav-1) are needed for the transport of cytosolic ENO-1 to the surface of breast cancer and monocytic cells." (PMID 25407528, 2014). "CAV1 (caveolin-1), has been identified as a marker associated with a basal-like phenotype in both hereditary and sporadic breast cancer, and has been proposed to play a role in intracellular cholesterol trafficking." (PMID 23408941, 2013). "Cancer-associated fibroblasts (CAFs), stromal cells with loss of caveolin-1 expression, have been implicated in this interaction in breast cancer because loss of caveolin-1 results from increased proteolysis by autophagy." (PMID 24020991, 2013). "Caveolin-1 can be detected at breast cancer diagnosis, which is important because high-risk patients would benefit from more aggressive antiangiogenic therapy." (PMID 22995409, 2012). "Cav-1 is a specific marker protein for caveolae and expression of Cav-1 was associated with the most aggressive ‘basal-like-phenotype’ breast cancer previously." (PMID 22496908, 2012). "Most of the current research on Cav-1 in breast cancer has demonstrated that loss of Cav-1 expression in the stromal cells surrounding the tumor is associated with early tumor recurrence and poor clinical outcome." (PMID 22356861, 2012). "Among each subgroup of patients, as grouped by prognostic factors such as hormone status, disease stage or lymph node status, a loss of stromal Caveolin-1 remained the strongest single predictor of breast cancer patient outcome." (PMID 22995409, 2012).
breast carcinoma (continued). "Loss of Cav-1 in stromal cells surrounding breast cancers has been associated with disease recurrence, metastasis, tamoxifen resistance and poor clinical outcome." (PMID 22356861, 2012). "A similar mammary tumor phenotype developed in caveolin-1 knockout mice that was also associated with the induction of several stem/progenitor cell markers, including RBM39, as found in the present study." (PMID 22538444, 2012). "For example, breast cancers with a loss of stromal caveolin-1 (Cav-1) generate higher levels of reactive oxygen species (ROS), as compared to breast cancers expressing high levels of stromal Cav-1." (PMID 21605374, 2011). "Among the top discriminators, CAV1 has been found to be down-regulated in breast cancer, and has been reported to be associated with metastasis in lung cancer." (PMID 21060876, 2010). "Recently, we identified a loss of stromal caveolin-1(Cav-1) as a novel biomarker for the cancer-associated fibroblast phenotype inhuman breast cancers." (PMID 20442453, 2010). "Independently, ourprevious data demonstrated that a loss of stromal Cav-1 protein expression (byimmuno-histochemistry) in human breast cancers is specifically associated witha 2.6-fold increase in the number of tumor cell positive lymph nodes(LN-metastasis)." (PMID 20442453, 2010). "Thiscould provide a molecular basis for understanding the lethality of a loss ofstromal Cav-1 in human breast cancer patients." (PMID 20442453, 2010). "In breast carcinomas, caveolin-1 overexpression has also been associated with metastasis and poor patient prognosis." (PMID 18400052, 2008). "This conclusion is further sustained by the fact that caveolin-1 presence is also associated with enhanced cell cycle progression in hormonedependent breast cancer cells stimulated with a progesterone analogue." (PMID 18400052, 2008). "Analysis of patients identified a P132L mutation in caveolin-1 in about 16% of breast cancer samples analyzed." (PMID 18400052, 2008). "Caveolin 1 (CAV1), the principal component of caveolae, has been associated with progression of colon and breast carcinomas and with enhanced invasiveness in lung adenocarcinoma cells." (PMID 18694510, 2008). "Among the genes selectively altered in basal-like breast cancer are those encoding p27 and caveolin-1." (PMID 17764562, 2007). "In a tumor progression model of breast cancer, loss of cav-1 corresponded to increased metastasis, while ectopic expression of cav-1 inhibited metastasis." (PMID 15969750, 2005). "Notably, EHD2 and CAV1 mRNAs were found to be coordinately expressed and jointly associated with shorter survival in basal breast cancer." (PMID 38959243, 2024). "In order to promote a novel phenotype in normal fibroblasts, we predicted that breast cancer cells could be able to cause loss of Cav1 and increase of MCT4, as well as elevate IL-6 and TGFβ in nearby normal fibroblasts." (PMID 38361760, 2024). "Moreover, we show that long-term co-culture of breast cancer cells and normal fibroblasts promotes loss of Cav1 and gain of MCT4 in adjacent fibroblasts and increase lactate secretion." (PMID 38361760, 2024). "Cav-1 downregulation may play a critical part in maintaining the aberrant status of breast-cancer-associated fibroblasts." (PMID 37496657, 2023). "Here, we investigated CAV1 polymorphisms in relation to clinical outcomes in breast cancer." (PMID 37017811, 2023). "Caveolin-1 (Cav1) loss in the tumor stromal compartment is a novel clinical biomarker for predicting poor outcome in breast cancer including triple negative subtype, however the mechanism of Cav1 loss is unknown." (PMID 37822942, 2023). "Therefore, mutation or low expression of Cav-1 is undoubtedly a factor promoting the progression of ERα (+) breast cancer." (PMID 37828916, 2023). "Caveolin-1 (CAV1) has been implicated in breast cancer oncogenesis and metastasis and may be a potential prognosticator, especially for non-distant events." (PMID 37017811, 2023).
breast carcinoma (continued). "Several CAV1 SNPs have been linked to multiple cancers, but the prognostic impact of CAV1 SNPs in breast cancer remains unclear." (PMID 37017811, 2023). "However, until now, there has been no unified understanding of the mechanism of the association between Cav-1 and breast cancer." (PMID 37828916, 2023). "Here, we investigated whether CAV1 genotypes and haplotypes impact prognosis, especially risk for metachronous contralateral breast cancer and locoregional recurrence, in primary breast cancer." (PMID 37017811, 2023). "Therefore, breast cancer with high expression of Cav-1 protein is often associated with better albumin-paclitaxel treatment." (PMID 37828916, 2023). "In addition, in breast cancer tumor tissues of ERa (+) breast cancer patients, Cyclin D1 overexpression was also observed in samples with Cav-1 mutations." (PMID 37828916, 2023). "The clinical significance of Cav1 stromal loss and its associated prognostic value in breast cancer has been known for some time and yet the mechanism of its loss remains unknown." (PMID 37822942, 2023). "In breast cancer, Cav1 has been shown to be strongly associated with clinical outcomes." (PMID 37822942, 2023). "A decrease in the transcription levels of human invasion signature (HIS) genes (ARHGDIB, CAPZA2, PHACTR2, CDC42, XRCC5, and CAV1) has been also demonstrated by real-time PCR, with high expression of these genes being a hallmark of actively metastasizing breast cancer cells." (PMID 36143471, 2022). "HSPB1 levels were found to be lower in caveolin-1-deficient breast cancer cells, and the treatment of keratinocytes with agents such as filipin or methyl-β-cyclodextrin that disrupt lipid raft-caveolae suppressed sulfur mustard-induced HSPB1 mRNA and protein expression." (PMID 35806322, 2022). "The role of CAV-1 in cancer progression might be linked to the different physiological functions of breast cancer in different stages." (PMID 36604141, 2022). "Moreover, CAV1 protein levels in TCGA were associated with two reactive breast cancer subgroups with an activated TME." (PMID 35660849, 2022). "Loss of stromal CAV1 in human breast cancer was associated with a poor clinical outcome." (PMID 36233075, 2022). "In addition, the clinical and experimental data of Simpkinset al. showed that CAV-1 deficiency in CAFs can enhance the invasiveness of BCCs and is related to the prognosis of breast cancer patients." (PMID 36604141, 2022). "Previous studies have shown COX-2 and CAV-1 colocalization at the plasma membrane of cancer-associated fibroblasts, as well as the positive correlation of their expression within plasma membrane caveolae-like structures in lobular breast cancer cells." (PMID 36471782, 2022). "Furthermore, we found that CEMM marker CAV1 is decreased in breast cancer patients and that the CEMM deficiency-induced autophagy is related to doxorubicin resistance, which is overcome by autophagy inhibition." (PMID 34786475, 2021). "In addition, we found the CAV1 downregulation is significantly associated with poor prognosis in patients with breast cancer by log rank test in the clinical data from Gene Expression Omnibus (GEO) datasets (GSE1456, 159 patients; GSE3494, 251 patients)." (PMID 34786475, 2021). "Caveolin-1 was also reported to associate with breast cancer stem cell enrichment." (PMID 34513683, 2021). "It was found that Cav-1 knockdown by Cav-1 specific siRNAs could significantly promote lactate production, ECARs and the expression levels of glycolysis-associated proteins in breast cancer cells." (PMID 34568078, 2021). "Interestingly, we found that the CAV1-deficient cells developed a dramatic resistance to Doxo (a first-line drug for breast cancer) when compared with CAV1-proficient cells (from half-maximal inhibitory concentration [IC50] = 6.62 to IC50 = 51.06)." (PMID 34786475, 2021).
breast carcinoma (continued). "The BRCA1 mutation in breast cancer cells has been shown to significantly increase ROS levels in adjacent fibroblasts, thus leading to decreased Cav-1 expression and increased expression of monocarboxylate transporter 4 (MCT4), which is the main exporter of L-lactate from cells." (PMID 33498875, 2021). "Previous studies have proven that Cav-1 is closely implicated in the metabolic modulation of breast cancer cells and could impair their glycolytic activity." (PMID 34568078, 2021). "Additionally, increasing studies also revealed that Cav-1 downregulation or loss usually occurred in tumor tissues of multiple transgenic breast cancer-prone mice." (PMID 34568078, 2021). "Downregulation of CEMM by CAV1 deficiency is associated with poor clinical outcome in breast cancer patients and might be involved in the Doxo resistance." (PMID 34786475, 2021). "Loss of CAV1 by genetic manipulation or functional defects fosters dysplastic lesions and this is a common feature of different types of cancers, including breast cancers." (PMID 32825330, 2020). "Loss of CAV1 function is a common feature of different types of cancers, including breast cancer." (PMID 32825330, 2020). "Altogether, Cav-1 loss could accelerate mouse mammary-tumor formation in vivo by activating the aerobic glycolysis activity of BCSCs." (PMID 32528105, 2020). "Furthermore, Cav-1 loss was associated with accelerated mammary-ductal hyperplasia and mammary-tumor formation in transgenic mice, which was accompanied by enrichment and enhanced aerobic glycolysis activity of BCSCs." (PMID 32528105, 2020). "Considering that Cav-1 downregulation was associated with a poor overall survival and an accelerated breast cancer onset, we speculate that Cav-1 may become a diagnostic and prognostic biomarker for breast cancer patients in the future." (PMID 32528105, 2020). "Thus, at least in this metastatic breast cancer cell model, CAV1 presence in EV preparations is associated with the accumulation of specific metastasis-related components." (PMID 31362353, 2019). "In addition, loss of stromal Cav-1 is associated with early disease recurrence, poorer progression free survival, and tamoxifen-resistance in breast cancer patients." (PMID 30348118, 2018). "CAV1 has been repeatedly linked to cancer progression, either as a tumor suppressor, as its absence is associated with a poor prognosis (e.g., aggressive prostate cancer, breast cancer, and gastric cancer), or as a tumor and metastasis promoter." (PMID 30246033, 2018). "The cohort was examined for two CAF-associated proteins with putative prognostic significance: tenascin-C, which has been shown to be up-regulated in a number cancers, and caveolin-1, the loss of which is a strong predictor of overall survival in breast cancer and is a promising marker in NSCLC." (PMID 29416729, 2018). "As to breast cancer, CAV1 overexpression is associated with poor clinical outcome." (PMID 29099748, 2017). "The initial studies focussed on breast cancer, but more recently it became clear that the loss or the weak expression of CAV1 in the cancer stroma is correlated with adverse prognosis for a variety of cancers, such as gastric cancer, pancreatic adenocarcinoma, prostate cancer, and colorectal cancer." (PMID 28515480, 2017). "Breast cancer patients with loss CAV1 expression in stromal cells were associated with shorter survival time, increased risk of early tumor recurrence, higher recurrence rate and metastasis, higher CAV1 expression in tumor cells were associated with poor survival." (PMID 29190968, 2017). "Paracrine/autocrine activation of NGF signaling has been implicated in tumor progression, cell survival and metastasis and deletion or mutation of Cav-1 have been reported for certain cancers, notably breast cancer while overexpression has been observed in certain prostate cancer lines." (PMID 28338624, 2017).
breast carcinoma (continued). "For example, reduced stromal expression of cav-1 has been associated with a poor prognosis, decreased disease-free survival, tumor invasiveness, lymph node metastases, and hormone receptor status in patients with breast cancer." (PMID 28187162, 2017). "Furthermore, loss of stromal CAV1 in human breast cancer is associated with increased tumour recurrence, metastasis and poor clinical outcome." (PMID 27852311, 2016). "Moreover, we found strong correlations between tumor grade, tumor stage, and 5-year breast cancer survival with Cav-1 expression level, with low Cav-1 expression being associated with higher tumor grade and lower 5-year survival." (PMID 26543228, 2016). "Shi's group also demonstrated that Cav-1 deficiency could induce autophagy via enhancing lysosomal function and autophagosome-lysosome fusion in human breast cancer cells." (PMID 26431273, 2015). "In addition, as early as 2001, Hayashi's group reported that the Cav-1 mutant form P132L was identified in 16% of primary breast cancers and mutation-positive cases were mostly invasive scirrhous carcinomas." (PMID 26431273, 2015). "As a model system to study the effects of tagging on transiently overexpressed Cav1, we compared the behavior of wild-type Cav1 and P132L Cav1, a breast cancer associated mutant that is mistrafficked in cells by mechanisms thought to involve defects in the oligomerization of the protein." (PMID 25639341, 2015). "Likewise, mammary tumors grown in a Cav-1-deficient tumor microenvironment were more aggressive than tumors grown in a wild-type microenvironment." (PMID 26284191, 2015). "However, the underlying mechanisms by which caveolin-1 suppresses breast cancer proliferation and metastasis remain understudied." (PMID 25397596, 2014). "A proteomic analysis was conducted in support of this hypothesis, this mechanism is mediated by the strong downregulation of the expression of caveolin-1 in fibroblasts that are associated with the stroma in breast cancer." (PMID 24857919, 2014). "Moreover, a loss of stromal Cav-1 has been reported to be a predictor of early tumor recurrence, lymph node metastasis, tamoxifen resistance, and poor clinical outcome in human breast cancer patients." (PMID 24949874, 2014). "BKCa channels are associated with caveolin-1 in human breast cancer MCF-7 Cells." (PMID 25397596, 2014). "Similarly, the loss of stromal Cav-1 expression predicts poor clinical outcome in triple negative and basal-like breast cancers." (PMID 25202343, 2014). "In addition, it was reported that high levels of CAV1 in the stromal breast cancer tissue were associated with reduced frequency of nodal metastasis and improved survival." (PMID 24229053, 2013). "Studies of breast cancer have revealed that the loss of Cav-1 in cancer-associated fibroblast cells (CAFs) promotes breast cancer proliferation and progression by remodeling the tumor microenvironment, protecting cancer cells from apoptosis and other mechanisms." (PMID 23203033, 2012). "As theprognostic value of a loss of stromal Cav-1 was independent of epithelialmarker status, it appears that a loss of Cav-1 has predictive value in all thedifferent epithelial subtypes of human breast cancer, including ER+, PR+,HER2+, and triple-negative patients." (PMID 20442453, 2010). "Interestingly, additional caveolin-1 mutations have recently been found associated with oestrogen-receptor α-positive breast cancers." (PMID 18400052, 2008). "Moreover, in breast cancer, the loss of caveolin-1 in stromal fibroblasts is observed to be an independent predictor of nodal metastasis, tumor recurrence, and poor clinical prognosis, whereas elevated levels of caveolin-1 are associated with increased survival." (PMID 39858015, 2025). "Importantly, loss of stromal CAV-1 is associated with poor patient outcomes in breast cancer." (PMID 37181035, 2023). "However, cytoplasmic CAV1 was associated with increased contralateral breast cancer risk." (PMID 35660849, 2022).